INS (insulin)
Diseases named in the same sentence as INS in open-access papers (continued):
Sharing a sentence is not in itself a finding about the gene and the disease.
Insulin resistance (continued). "MET is an insulin sensitizer that reduces insulin levels and improves insulin receptor activity, resulting in decreased insulin resistance, lower androgen levels, and improved weight control." (PMID 37002532, 2023). "In obesity, the persistent increase in free fatty acids worsens insulin resistance by triggering inflammation and disrupting insulin signaling pathways." (PMID 38283440, 2023). "In contrast, anti-inflammatory molecules (e.g., adiponectin, IL-10) that enhance insulin sensitivity and endothelial function are suppressed and insulin resistance is increased." (PMID 36844000, 2023). "The dysfunction of insulin action leads to insulin resistance, resulting in abnormal plasma glucose concentration with increased glucose production and decreased glucose uptake." (PMID 37513589, 2023). "In terms of immunosuppression, changes in insulin secretion were primarily associated with CNI, whereas insulin resistance was related to corticosteroid use." (PMID 37424863, 2023). "Insulin profiles and indices—a variety of methods of calculating insulin resistance/sensitivity and insulin secretory response using timed insulin and glucose during the OGTT for GDM subtyping were described." (PMID 38110524, 2023). "The results of the study revealed that the expression of p-AKT (phosphorylated AKT) was lower in the non-insulin resistance group compared to the insulin-resistant group, which had higher p-AKT expression." (PMID 37062827, 2023). "Serum concentrations of several pro-inflammatory cytokines inhibit insulin signaling, which results in signal redundancy since insulin resistance induces inflammation and vice versa." (PMID 36976988, 2023). "T2DM is a complex glucose and lipid metabolism-associated disease mainly characterized by hyperglycemia arising from insulin resistance and/or insufficient insulin secretion (Chatterjee, Khunti & Davies, 2017)." (PMID 37361044, 2023). "All the results showed that inhibiting NLRP3 inflammasome activation can restore the IR-IRS-AKT-AS160 insulin signaling pathway to alleviate insulin resistance in the 3×Tg-AD mice." (PMID 36978970, 2023). "This includes both attenuated insulin-responsive phosphorylation, and the emergence of phosphorylation uniquely insulin-regulated in insulin resistance." (PMID 36808134, 2023). "These metabolites and targets mainly enrichment pathways involving endocrine-related pathways (estrogen signaling pathway, insulin resistance, and insulin secretion), and signal transduction (PI3K-Akt, MAPK, and Jak-STAT signaling pathways)." (PMID 37334310, 2023). "Phloretin treatment also resulted in a significant (p < 0.01, p < 0.001, respectively) reduction in blood glucose and serum insulin levels thereby maintaining homeostasis model assessment-estimated insulin resistance (HOMA-IR)." (PMID 37744933, 2023). "Lowering insulin levels, insulin resistance, and plasma total cholesterol, while reducing white blood cell count and blood lipopolysaccharide levels." (PMID 38192650, 2023). "IN insulin is currently being investigated in the clinic as a therapy to delay cognitive decline in patients that likely have CNS insulin resistance." (PMID 37076875, 2023). "During the second trimester, insulin resistance becomes higher, and levels of glucose increase in women who are unable to produce an adequate amount of insulin." (PMID 37664380, 2023). "Understanding more about the regulation of insulin transport into the brain will help us understand how brain insulin resistance arises and suggest therapeutic targets for prevention." (PMID 37076875, 2023). "This condition is associated with increased androgen production (hyperandrogenism) and decreased insulin sensitivity, which often leads to insulin resistance and hyperinsulinemia." (PMID 37569074, 2023). "We also used the fasting insulin level as an exposure factor, which provides a proxy for the degree of insulin resistance." (PMID 37900148, 2023).
Insulin resistance (continued). "Obesity and T2D commonly display insulin resistance, characterized by a reduced responsiveness of the body’s cells to insulin." (PMID 37600709, 2023). "It’s worth highlighting that FIns represents both insulin secretion and resistance, and frequently serves as a surrogate marker for insulin resistance in extensive studies." (PMID 38066511, 2023). "Another validated index is the homeostasis model assessment of insulin resistance (HOMA-IR) calculated by dividing serum glucose by insulin concentrations." (PMID 37542255, 2023). "Arsenic can also alter p38 MAPK signaling and insulin-stimulated glucose absorption, leading to insulin resistance and T2D." (PMID 37396849, 2023). "GDM is described as insulin resistance, usually diagnosed in the second or third trimester, resulting from insulin attenuation and diminished glucose metabolism." (PMID 37200795, 2023). "They measured blood glucose levels, insulin levels and calculated the Homeostatic Model assessment of insulin resistance (HOMA-IR)." (PMID 37552651, 2023). "Their plasma insulin concentrations were found to be higher than in healthy individuals as a result of insulin resistance." (PMID 37089422, 2023). "Long-term hyperglycemia in mice will destroy insulin homeostasis, reduce insulin sensitivity, and eventually produce insulin resistance symptoms." (PMID 37893758, 2023). "It is also believed that insulin resistance, glucose intolerance, elevated plasma insulin levels, body mass index (BMI), insulin-like growth factor (IGF-1), serum glucose, and free fatty acids are associated with the pathogenesis of colorectal cancer." (PMID 37568613, 2023). "The age-related loss of muscle mass has harmful effects on peripheral glucose absorption through reduced muscle mass for insulin-stimulated glucose disposal, which further leads to hyperinsulinemia status and insulin resistance." (PMID 37775740, 2023). "It has been reported that the expression of autophagy-related genes is downregulated in the endometrium of women with PCOS and insulin resistance, and metformin (an insulin-sensitizing drug) counteracts these alterations." (PMID 37876013, 2023). "Based on previous studies, we know that there is a degradation of Adipo during insulin resistance, which can also lead to a decrease in Adipo levels and thus an inability to maintain normal insulin sensitivity." (PMID 37034166, 2023). "The studies showed that short sleepers had greater levels of circulating insulin during fasting, fasting glucose, and homeostatic model assessment for insulin resistance (HOMA-IR)." (PMID 38050514, 2023). "T1D can be associated with metabolic disorders and several impaired pathways, including insulin signaling, and development of insulin resistance through the renin-angiotensin system (RAS)." (PMID 38092813, 2023). "Insulin resistance (IR) impairs insulin's beneficial effects on the brain and can change the course of illness in post-stroke patients." (PMID 38034217, 2023). "Insulin resistance refers to the body’s decreased ability to respond to the hormone insulin, leading to elevated insulin levels in the bloodstream." (PMID 37762850, 2023). "After insulin resistance, a large amount of insulin accumulated in the body will inhibit fat decomposition and promote the production of the liver and peripheral fat, leading to obesity." (PMID 37547098, 2023). "During chronic overfeeding, augmented insulin secretion counteracts insulin resistance, thereby preventing hyperglycemia." (PMID 36821378, 2023). "Insulin resistance refers to the inability of cells to effectively use insulin, leading to high levels of insulin (hyperinsulinemia) in the body." (PMID 37274075, 2023). "Insulin resistance is a complex phenomenon that occurs when cells in the body become less responsive to the effects of insulin, a hormone produced by the pancreas." (PMID 38002034, 2023).
Insulin resistance (continued). "Published observations underscore the importance of mTORC1 signaling on modulation of β-cell mass, insulin secretion and adaptation to insulin resistance." (PMID 37423392, 2023). "Serum hs-CRP was shown to be positively correlated with serum insulin, insulin resistance, fat mass, and body weight in women with PCOS26,27." (PMID 37355686, 2023). "IFG is mainly caused by increased hepatic insulin resistance and impaired basal insulin secretion, while IGT mainly results from peripheral insulin resistance and reduced stimulated insulin secretion." (PMID 36897358, 2023). "Obesity-induced insulin resistance was proven by increased insulin levels in WKY rats fed a HF diet, both 60 and 66 weeks old, which resulted in a high HOMA index." (PMID 36678151, 2023). "In the case of insulin resistance, insulin signal transduction is disrupted by protein modifications such as phosphorylation and dephosphorylation, O-GlcNAcylation, and ubiquitination of either signaling molecule." (PMID 36834633, 2023). "The condition that precedes T2DM is insulin resistance (IR), which is identified as an impaired biological response to insulin stimulation of target tissues, primarily the liver, muscle and adipose tissue." (PMID 37686368, 2023). "Insulin resistance and impaired insulin secretion are the two main components in the pathophysiology of T2DM." (PMID 37792730, 2023). "Ceramides play essential roles in insulin resistance due to their ability to inhibit insulin-stimulated glucose transport." (PMID 38274826, 2023). "Measurements of skeletal muscle β‐catenin levels prior to the development of insulin resistance and rescue experiments where β‐catenin overexpression is triggered in already insulin‐resistant muscle would be key to determining the direction of causality." (PMID 36807886, 2023). "Studies testing the efficacy of insulin-sensitizing strategies, such as lifestyle changes and thiazolidinediones, for ameliorating CV outcomes in people with insulin resistance have shown positive effects." (PMID 37568149, 2023). "In this study, patients taking selenium and probiotics had decreased levels of serum hs-CRP, insulin, and homeostasis model of assessment-insulin resistance (HOMA-IR)." (PMID 36749772, 2023). "Collectively, phosphoproteomic analysis of in vivo models of insulin resistance recapitulated key findings from 3T3-L1 adipocytes, including the observation that regulation of GSK3 by insulin is impaired in insulin resistance." (PMID 36808134, 2023). "The precursors of T2D can be identified by an overproduction of insulin in an attempt to maintain normal glucose levels despite insulin resistance, as seen in a study on normal and obese people." (PMID 37049602, 2023). "The mechanism underlying the hypoglycemic effect of SPP regulates the mRNA expression of key PI3K/Akt genes involved in the insulin signaling pathway to alleviate insulin resistance." (PMID 36677586, 2023). "If left unchecked, pro-inflammatory cytokines derived from adipose tissue go on to disrupt insulin signaling, which can lead to the development of insulin resistance, and eventually, type 2 diabetes." (PMID 37139450, 2023). "T2DM is characterized by insulin resistance, where the body cells cannot effectively respond to insulin action, which leads to hyperglycemia." (PMID 38203642, 2023). "Insulin resistance is characterized by an impaired response of the body to insulin, resulting in an impaired peripheral tissue glucose uptake." (PMID 37265574, 2023). "In insulin resistance, the normal insulin-mediated activation of PI3K/Akt signaling is impaired, disrupting the translocation of GLUT4 and glucose uptake." (PMID 37715850, 2023). "Given the robust link between PCOS and insulin resistance, multiple molecules acting as insulin sensitizers have been proposed to contrast the metabolic dysfunction observed in both conditions." (PMID 36826058, 2023).
Insulin resistance (continued). "By understanding the nuances of NADPH’s role in insulin signaling, the scientific community can move closer to unraveling the complex web of metabolic dysfunction that characterizes insulin resistance." (PMID 38203517, 2023). "A previous study showed that fasting and 2-h post glucose serum insulin levels as well as insulin resistance measured using HOMA-IR had a strong relationship with BW and BMI." (PMID 36627590, 2023). "Taken together, these findings suggested that ZFYVE28 expression was lower in obese subjects with normal insulin sensitivity, while it was elevated in subjects with insulin resistance." (PMID 37884540, 2023). "Insulin resistance refers to a condition in which the body’s cells become less responsive to the hormone insulin." (PMID 37512552, 2023). "While the main feature associated with preptin increase seems to be the presence of insulin resistance, physical exercise improves both insulin sensitivity and downregulates preptin concentrations, as demonstrated in male patients with prediabetes." (PMID 37755271, 2023). "Among the patients diagnosed with PCOS + HT, insulin resistance was found to be significantly correlated with fasting insulin, HOMA index, (BMI), (SHBG) and left ovarian volume." (PMID 36829146, 2023). "Insulin resistance is a condition in which cells fail to respond to the normal insulin actions, resulting in hyperglycemia due to impaired glucose utilization by the cells." (PMID 37422477, 2023). "This is an essential feature of ketogenic meals that would help to reduce hyperinsulinemia-driven insulin resistance and would help patients with limited insulin secretory capability to metabolize their food intake without developing significant hyperglycemia." (PMID 36904127, 2023). "It involves abnormal glucose, lipid, and protein metabolism, insulin resistance, and decreased insulin production." (PMID 37954695, 2023). "It has been demonstrated experimentally in mice that the activation of SirT1 optimizes the organism for metabolic adaptation to insulin resistance by improving hepatic insulin sensitivity and decreasing whole-body energy requirements." (PMID 37569434, 2023). "Although growth hormone has a role in insulin resistance in transition cows, there is strong evidence that long-chain sFFA operates as an antagonist of systemic insulin sensitivity." (PMID 38274826, 2023). "Correlation studies in all patients (n = 79) revealed that plasma hsa-miR-21-5p, expression level was positively correlated with serum insulin and the presence of insulin resistance and dyslipidemia (increased TC and TAG)." (PMID 36834570, 2023). "In a fed state, the normal blood glucose disposal in the skeletal muscle is maintained by GLUT4 translocation to the plasma membrane and the failure of this event in response to insulin shows an early stage of insulin resistance and T2DM." (PMID 37447192, 2023). "The formula fasting plasma glucose×fasting plasma insulin/22.5 was used to calculate homeostatic model assessment of insulin resistance (HOMA-IR)." (PMID 38129878, 2023). "Considering the established role of PI3K/AKT pathway in insulin-regulated metabolism and the development of insulin resistance, the phosphorylation levels of these proteins was detected via Western blotting both in vivo and in vitro." (PMID 37367037, 2023). "For final proof of insulin resistance, it would be necessary to perform a functional study—to apply insulin and determine the values of pAkt and pGSK3 in the tissue 1 h after insulin application." (PMID 37929025, 2023). "Insulin injections are currently the conventional treatment for T1DM, and prolonged overexposure to insulin itself is a trigger for insulin resistance." (PMID 37056675, 2023). "Enhanced inflammation, increased reactive oxygen spaces (ROS) production and faint antioxidant defense systems are responsible for the improper synthesis, secretion and action of insulin leading to insulin resistance." (PMID 37110134, 2023).
Insulin resistance (continued). "Some evidence shows that the sustained activation of mTOR downregulates insulin signaling in insulin-responsive cells and reduces insulin secretion in beta cells, which contributes to insulin resistance." (PMID 37049920, 2023). "Glucose and insulin tolerance tests were carried out to detect insulin resistance, and the Morris water maze was used to test the spatial learning and memory ability of the mice." (PMID 36978970, 2023). "M1 macrophages promote the progression of adipose tissue inflammation and insulin resistance by secreting pro-inflammatory cytokines capable of impairing insulin signaling." (PMID 36838843, 2023). "• Insulin resistance and deficit in insulin signaling pathway were demonstrated in neonatal skeletal muscle after only 2-day continuous hyperglycemia. • Aberrant mitochondrial dynamics and structure were seen in O-PGDM." (PMID 37255932, 2023). "It is noteworthy that the insulin resistance in metabolic syndrome presents with an increased concentration of circulating insulin." (PMID 36901725, 2023). "When a person has insulin resistance, the cells in their body cease reacting to insulin as they should and instead inhibit glucose absorption." (PMID 37383339, 2023). "By influencing important blood glucose metabolism enzymes, palmitoleic acid lowers insulin resistance in diabetics and controls insulin secretion in patients." (PMID 37841397, 2023). "The results showed that metformin and empagliflozin combination therapy reduced the high levels of insulin and ameliorated insulin resistance in PCOS‐IR as compared with empagliflozin alone." (PMID 37985173, 2023). "Nonetheless, it has been established that long-term muscle insulin resistance induces elevated plasma insulin levels, which stimulate lipogenesis and accelerate fat formation in the liver." (PMID 36819346, 2023). "There are a number of treatments that can reduce hyperglycemia in T2D patients by improving insulin secretion or reducing insulin resistance in peripheral tissues." (PMID 37153000, 2023). "Future work on optimising insulin dosing from the first trimester, with better matching of insulin to dietary intake and insulin resistance, is needed to improve maternal and neonatal health." (PMID 37615689, 2023). "Transgenic animal models have found increased GPx1 expression interferes with insulin signaling by removing hydrogen peroxide, leading to the development of insulin resistance, hyperglycemia, and obesity." (PMID 37275636, 2023). "Large quantity of replicated HBV in host will cause inflammatory necrosis of hepatocytes resulting in the reduced inactivation of insulin and glucagon, which will lead to impaired glucose tolerance and insulin resistance." (PMID 37077357, 2023). "During the second and third trimesters of pregnancy, anti-insulin hormones such as estrogen, progesterone, and cortisol promote the development of insulin resistance." (PMID 36986107, 2023). "This study found that insulin resistance regulates insulin signal transduction by mediating PI3K/Akt signaling pathways and promoting glucose transport." (PMID 37834276, 2023). "The pathogenesis of T2DM lies in defective insulin production by β-cells and/or insulin resistance in insulin-sensitive cells." (PMID 38132335, 2023). "The impairment of the insulin signal and insulin resistance was further confirmed in our NAFLD model by a significant decrease in the hepatic expression of IRS-2." (PMID 37261280, 2023). "BACH1 facilitated PTP1B binding to IR-β, suppressed insulin signaling, and aggravated insulin resistance in HFD-fed mice and diabetic mice." (PMID 38129407, 2023). "Potential mechanisms include insulin resistance, as insulin has been shown to exert a direct effect on glomerular podocytes, increased renal gluconeogenesis, and endothelial dysfunction/chronic inflammation." (PMID 37432359, 2023). "During pregnancy, the increase in demand for insulin due to insulin resistance is compensated by its increased production, even by 50%." (PMID 38203346, 2023).